CD38 (CD38 molecule)
Diseases named in the same sentence as CD38 in open-access papers (continued):
Sharing a sentence is not in itself a finding about the gene and the disease.
prostate carcinoma (continued). "Overexpression of CD38 in prostate cancer cells leads to an increase in pAMPK levels, a decrease in fatty acid and lipid synthesis, reduced glycolysis and metabolism, and an extended cell doubling time, ultimately resulting in a decrease in tumor cell proliferation." (PMID 40382743, 2025). "Studies have been showed that CD38 inhibited the metabolism and proliferation in prostate cancer." (PMID 38767825, 2024). "The role of CD38 in tumor progression has also been reported in prostate cancer, and multiple studies suggest that CD38 could be a potential immunotherapy target." (PMID 36439479, 2022). "CD38 expression is consistently silenced by methylation in prostate cancer and progressively downregulated in advanced castration-resistant prostate cancer, suggesting a connection between NAD+ and prostate carcinogenesis as well as prostate cancer progression." (PMID 35677882, 2022). "Interestingly, while expression of CD38 is lost in advanced prostate cancers, the expression of NAMPT is increased." (PMID 35677882, 2022). "Functional studies focusing on CD38 in prostate cancer have relied on prostate cancer cell lines." (PMID 35677882, 2022). "However, the data generated from studies on the influence of CD38 in prostate cancer are disparate from these findings." (PMID 31878283, 2019). "CD38 expression is reduced in prostate cancer compared to benign prostate, suggesting that tumor cells may reduce CD38 expression in order to enhance pools of NAD+." (PMID 30258629, 2018). "Low CD38 transcript levels are part of a set of 91 transcripts that define a basal/stem cell signature in prostate epithelial cells and this signature is enriched in aggressive and neuroendocrine-type castrate resistant prostate cancers." (PMID 29464091, 2018). "Based on low expression of CD38 in CRPC samples, we hypothesized that CD38 protein expression in primary prostate cancer may be predictive of disease progression." (PMID 30258629, 2018). "A graded decrease in CD38 protein expression has been observed in 23 prostate samples comparing normal prostate glands distant from cancer with normal glands adjacent to cancer, and with prostate cancer glands." (PMID 29464091, 2018). "Differential CD38 staining has been reported in prostate cancer by us." (PMID 20021671, 2009). "To determine whether high and low myosin IC isoform A expression correlated with distinct cell surface phenotypes, we extended our panel adding seven surface molecules (CD10, CD13, CD29, CD38, CD54, CD146, and CD166) that have been associated with the tumorigenic potential of prostate cancer cells." (PMID 34019593, 2021). "However, little is known about how CD38 expression is repressed in advanced prostate cancer and whether CD38 plays a role in regulating NAD+ levels in prostate epithelial cells." (PMID 30258629, 2018). "In summary, our studies demonstrated the functional impact of CD38 overexpression and NAM supplementation on prostate cancer cell viability, intracellular NAD+ level, and mitochondrial respiration." (PMID 35677882, 2022). "In this study, we focused on the functional impact of CD38 overexpression and subsequent NAM supplementation in prostate cancer using a doxycycline-inducible castration-resistant prostate cancer cell line model (LNCaP95)." (PMID 35677882, 2022). "The CD38 influence on NADH metabolism and related tumor signaling may explain such a role, and its anti-correlation with the expression of myosin 1C isoform A is consistent with this myosin’s proposed function as a prostate cancer progression-associated molecule." (PMID 34019593, 2021). "Compared to normal tissue, prostate cancer samples had also reduced numbers of CD24- and CD38-positive cells." (PMID 34019593, 2021). "Our data clearly demonstrate that CD38 and ARG2 identify three different differentiation states in prostate cancer." (PMID 29464091, 2018).
prostate carcinoma (continued). "Using gene expression data, we identified two markers, CD38 and ARG2, that group prostate cancer into three differentiation states." (PMID 29464091, 2018). "To investigate the role of CD38, we utilized the Tet-ON system to generate Dox-inducible stable lines using the CD38 negative castration-resistant LNCaP95 prostate cancer cell line." (PMID 35677882, 2022). "However, the functional interplay between NAD+, CD38, and NAM remains largely uncharacterized in prostate cancer cells." (PMID 35677882, 2022). "Prostate cancer cell lines are negative for CD38 and have been used to investigate the function of CD38 following gene overexpression." (PMID 35677882, 2022). "As prostate cancer has a lipogenic phenotype, the lack of fatty acid and lipid synthesis as a result of CD38 expression would likely be detrimental for successful tumorigenesis." (PMID 31878283, 2019). "We find evidence to support CD38 as a regulator of extracellular NAD+, suggesting that repression of CD38 expression in prostate cancer may serve to increase the pool of extracellular NAD+." (PMID 30258629, 2018). "CD38 was the most abundantly expressed marker and similarly to CD24 demonstrated a statistically significant decrease in prostate cancer samples compared to non-cancer tissue (p<0.01, Kruskal-Wallis test)." (PMID 34019593, 2021).
lymphopenia (22 papers, 2014 to 2025). Reduction in the number of lymphocytes. "Our meta-analysis suggests that while anti-CD38 monoclonal antibodies may be associated with an increased risk of severe lymphopenia, neutropenic infections, and thrombocytopenia, they also offer improved clinical efficacy in MM treatment." (PMID 38672988, 2024). "For memory CD4+ T-cells, we found that, although proliferation rates were associated with viral load and CD4 lymphopenia, the strongest association was with immune activation (HLA-DR/CD38 coexpression), although it should be noted that no markedly lymphopenic subjects were recruited." (PMID 24803534, 2014). "Lymphoid cell distribution revealed a CD19+ B cell lymphopenia (5%) with a reduction in CD24++CD38++ transitional B cell percentage (0.7%)." (PMID 39860371, 2025). "When confronting the investigated variables with 28-day mortality, it occurred that patients with fatal outcome presented more severe lymphocytopenia and higher frequency of activated lymphocytes with CD38+ and HLA-DR+ expression." (PMID 36992243, 2023). "In line with the multipotential function of HLA-DR expressing T cells, it has been shown that activated CD8+ T cells co-expressing of HLA-DR and CD38 accumulated over a prolonged period in HIV-infected lymphopenia patients." (PMID 36560637, 2022). "In regard to the impact of lymphopenia, lymphopenic patients had increased Th2, CD38+CD4+ T cells, HLA-DR+CD4+ T cells, and Tregs." (PMID 33324414, 2020). "The relationship between lymphopenia and the burst activation of CD38+HLA-DR+CD8+ T cells in high-grade glioma remains uncertain." (PMID 31649684, 2019). "CD38 has also been shown to be involved in cell adhesion and immune cells being uncontrollably activated, which could contribute to thrombosis and lymphopenia." (PMID 36675642, 2023). "Importantly, active treatment with either anti-CD38 monoclonal antibodies (Mabs) or belantamab mafodotin and lymphopenia at the time of vaccination were independent prognostic factors for suboptimal antibody response following vaccination." (PMID 34341335, 2021). "This was also confirmed in another study where they concluded that in infection with SARS-CoV-2, lymphocytopenia is a significant feature and that CD8+ and CD4+ T cells are overactivated, as demonstrated by the expression of HLA-DR/CD38 resulting in dysregulation of NAD+ metabolism." (PMID 36675642, 2023). "Conversely, though the early prominence of an activated CD38+HLA-DR+PD-1+CD8+ set is associated with survival, the combination of lymphopenia with a high frequency of (perhaps) IAV-non-specific CD38+HLA-DR+PD-1+CD8+ T cells is characteristic of fatal disease." (PMID 29483513, 2018). "Active treatment with regimens including belantamab mafodotin or anti-CD38 monoclonal antibodies that deplete B-cells, as well as lymphopenia, were negative prognostic factors at the multivariate analysis, as they were correlated with lower antibody response rates." (PMID 34341335, 2021). "The absolute numbers of CD19+CD5+CD1dhigh cells, CD19+CD24+CD38+ cells, and CD19+IL-10+ cells increased but not significantly in SLE patients when compared with healthy controls, which might be attributed to peripheral lymphopenia in SLE patients during flares." (PMID 24551101, 2014).
dengue (21 papers, 2010 to 2025). "CD38 which was identified, verified and tested in independent datasets could distinguish three clinical stages of Dengue fever and was significantly associated with plasma cells, but it could not use to predict severity which was similar to precious results and distinguish different serotypes." (PMID 35918744, 2022). "The expressions of CD38 and human leukocyte antigen-DR (HLA-DR) were used to assess the level of T-cell activation in both acute and chronic infections, such as dengue and HIV, and in M. tuberculosis infection." (PMID 37947190, 2024). "CD38 and Plasma cells have excellent Area Under the Curve (AUC) in distinguishing clinical stages for Dengue patients, and activated memory CD4+ T cells and Monocytes have good AUC for this function." (PMID 35918744, 2022). "In dengue virus infection, expression of CD38 on MAIT cells was higher in individuals who progressed to dengue hemorrhagic fever, suggesting that MAIT cell activation is associated with a more severe disease." (PMID 33763658, 2021). "We therefore analysed Granzyme B function in acute dengue and found this followed the same time course as that of CD38." (PMID 27337592, 2016). "We conclude that both HLA-DR+ CD38+ and HLA-DR− CD38+ activated CD8 T cells in dengue patients are massively expanding, express markers of tissue homing, and are equipped with cytotoxic effector functions." (PMID 27707928, 2016). "HLA-DR+ CD38+ CD8 T cells were sorted from the PBMCs of seven dengue patients from Siriraj Hospital in Bangkok, Thailand." (PMID 27707928, 2016). "In contrast, dengue cases showed significantly higher CD8 T cells expressing CD38 in all disease status and still in convalescent group compared to controls." (PMID 22815692, 2012). "Strikingly, in dengue patients we observed a large population of surface-activated (CD38+ or HLA-DR+) and proliferating (Ki-67+) CD8+ T cells at early convalescence that were mostly absent at the time of enrolment and follow-up." (PMID 20706626, 2010). "We selected CD38 as a biomarker for staging diagnosis of Dengue." (PMID 35918744, 2022). "Analysis of HLA-DR+CD38+ and HLA-DR-CD38+ effector CD8 T cells in dengue-infected patients from India and Thailand displayed the expansion of both the subsets in these patients, while the effector qualities were more prominent in HLA-DR+CD38+ CD8 T cells and were mostly directed against NS3." (PMID 36423184, 2022). "Regarding CD38 and HLA-DR expression on T cells, we observed that 8 donors showed a higher T cell activation in response to L1 than to L6 isolates; those included six dengue naive and two with undetermined serology." (PMID 29813061, 2018). "Moreover, our results from India and Thailand are consistent with previous studies reporting expansion of HLA-DR+ CD38+ and HLA-DR− CD38+ cells in dengue patients from Brazil and Vietnam." (PMID 27707928, 2016). "Interestingly, our results showed that these HLA-DR− CD38+ single-positive CD8 T cells also substantially increased in the dengue patients." (PMID 27707928, 2016). "Therefore, CD38 shows the high value in distinguishing stages for Dengue patients." (PMID 35918744, 2022). "In another study of stage-related and severity-related biomarkers, they have found CD38 and ZNF595 as significant biomarkers; CD38 can distinguish different clinical stages of dengue, while ZNF595 can differentiate between dengue fever (DF) and DHF." (PMID 40100920, 2025). "Proportions of CD8+CD38+ HLA-DR+ and CD8+CD38+ cells were significantly increased in dengue fever patients compared to healthy controls." (PMID 35392095, 2022). "CD38, Plasma cells, activated memory CD4+ T cells and Monocytes can be used to distinguish clinical stages for dengue patients, and ZNF595 can be used to discriminate DHF from DF, regardless of serotypes." (PMID 35918744, 2022).
dengue (continued). "Our analysis of dengue patients from Thailand showed that the average frequencies and numbers of the two activated CD8 T cell subsets (HLA-DR+ CD38+ and HLA-DR− CD38+) were also similar in dengue patients from Thailand." (PMID 27707928, 2016). "These HLA-DR+ CD38+ CD8 T cells average about 0.2 × 106 cells per ml blood and reached as high as 1 × 106 per ml blood in some of the dengue patients (right)." (PMID 27707928, 2016). "From these data, we conclude that both HLA-DR+ CD38+ and HLA-DR− CD38+ CD8 T cell subsets proliferate and expand massively in dengue patients." (PMID 27707928, 2016). "Here, we provide a detailed analysis of HLA-DR+ CD38+ and HLA-DR− CD38+ effector CD8 T cell subsets in dengue patients from India and Thailand." (PMID 27707928, 2016). "By using a combination of phenotypic, functional, and transcriptomic approaches, our studies revealed that both HLA-DR+ CD38+ and HLADR− CD38+ CD8 T cell subsets expanded massively in dengue patients." (PMID 27707928, 2016). "Interestingly, patients who developed the severe form of dengue had higher levels of MAIT cell activation as judged by CD38 expression compared to DF patients over the course of acute infection." (PMID 27337592, 2016). "The frequency of the HLA-DR+ CD38+ CD8 T cells was generally low (average, 1.5%) in healthy subjects, but these cells expanded dramatically in the dengue patients (left)." (PMID 27707928, 2016). "The HLA-DR+ CD38+ CD8+ T cells have been shown to expand and express marker genes for proliferation, tissue homing, and cytotoxic functions; as well as become unresponsive to IFN-gamma and develop TCR refractoriness in dengue patients." (PMID 35345453, 2022). "The GSEA showed that the 500 most upregulated genes identified from our sorted HLA-DR+ CD38+ CD8 cells positively correlated with upregulated genes during dengue virus infection compared to healthy controls or non-dengue infection from other studies." (PMID 27707928, 2016). "Because CD38 and CDKN1C express differently in three stages, we speculate that they can be used as biomarkers with staging characteristic to distinguish clinical stages for Dengue patients." (PMID 35918744, 2022). "Our research was the first to show that CD38 and ZNF595 had clinical significance in the stage and severity of Dengue and that they could be used as biomarkers to distinguish clinical stages and severity for Dengue patients." (PMID 35918744, 2022). "Hence, we performed a comprehensive immune phenotyping of the HLA-DR+ CD38+ double-positive, HLA-DR− CD38+ single-positive, and HLA-DR− CD38− double-negative CD8 T cell subsets from the dengue patients." (PMID 27707928, 2016). "The proportion of CD4 T cells expressing CD38 was not altered in dengue cases compared to controls." (PMID 22815692, 2012). "Moreover, NS1 TET+ and total NK cells were activated to express CD38 during the critical phase of DENV illness only in HLA‐B57+ patients with DHF, suggesting that NK cell subsets may contribute to the immunopathogenesis of dengue disease." (PMID 26439909, 2016).
glioma (21 papers, 2015 to 2025). A benign or malignant brain and spinal cord tumor that arises from glial cells (astrocytes, oligodendrocytes, ependymal cells). "An increase in activated CD8+ T cells, characterized as CD38+HLA-DR+, and their association with disease progression were identified in the patients' peripheral blood and glioma, and shown to display enriched CCR5+ and TNFR2+ expression levels." (PMID 31649684, 2019). "Increases of IFN-γ and Granzyme B underlying CCR5+CD38+HLA-DR+CD8+ T cell activation were observed after co-culturing with glioma cells." (PMID 31649684, 2019). "Upstream regulators inhibited at the same early time point include CSF2, which supports M1 macrophage polarization, and CD38, whose loss attenuates glioma progression." (PMID 25952672, 2015). "In gliomas, CD38 expression is closely associated with tumor invasiveness and patient prognosis." (PMID 40677211, 2025). "In gliomas, the expression of CD38 in the TME has been associated with F4/80 infiltrating microglia and macrophages, which favor tumor growth, and suggest that CD38 may play a role in the recruitment and survival of these immune subpopulations." (PMID 33467713, 2021). "Moreover, CD38 deficiency regulated microglia activation through microglia-associated mechanisms to attenuate glioma progression, and it could modulate tumor-associated microglia/macrophage characteristics, which was also consistent with our study." (PMID 36778644, 2023). "Studies have confirmed that CD38 can regulate microglial activation in vitro and in vivo, and its absence can inhibit glioma progression." (PMID 39744577, 2025). "The NMRGS score of every glioma patient was obtained as follows: NMRGS score = (-0.28992*CD38 expression) + (0.38315*NADK expression) + (-0.04654*NAPRT expression) + (0.2211*NMNAT3 expression) + (-0.24486*PARP6 expression) + (0.29991*PARP9 expression)." (PMID 36845744, 2023). "In glioma cells, CD38 has an impact on the intracellular ATP levels and the survival of C6 glioma cells, which makes CD38 a potential therapeutic target for gliomas." (PMID 36077708, 2022). "According to a study, the proliferation of gliomas can be inhibited by inhibiting CD38, thereby prolonging the survival time of glioma mice." (PMID 34881075, 2021). "In the present study, we investigated the activation of the CD38+HLA-DR+CD8+ subpopulation among total human CD8+ cells along with their penetration into the tumor microenvironment in a large series of glioma samples." (PMID 31649684, 2019). "In this present study, we demonstrated the functional expression of CCR5 on CD38+HLA-DR+CD8+ T cells and the presence of CD45RA+CCR7− underling CCR5+CD38+HLA-DR+CD8+ T-cell activation in patients with glioma." (PMID 31649684, 2019). "Several effector molecules, including CD107a, IFN-γ, and Granzyme B, coincided significantly with CCR5+CD38+HLA-DR+CD8+ T cells after contact with the U87 glioma cells." (PMID 31649684, 2019). "Analysis of subpopulations of tumor-associated microglia/macrophages (TMM) revealed that F4/80 macrophages were found to be significantly reduced in glioma-bearing CD38 KO mice." (PMID 31878283, 2019). "In the present study, we also found an elevation of CCL5 in the glioma microenvironment, which is in accordance with the infiltration of CD38+HLA-DR+CD8+ TILs via CCR5 expression." (PMID 31649684, 2019). "The functional expression of CD38 and HLA-DR was reported to reflect infection status as it related to survival capacity in glioma." (PMID 31649684, 2019). "Similar studies completed in glioma transplantation models of cancer have found that CD38 null mice have reduced glioma expansion and extended life spans as compared to glioma bearing wildtype mice." (PMID 31878283, 2019). "We showed previously that targeting CD38 in the glioma microenvironment inhibited glioma progression, and that this effect was mediated by microglia/macrophages." (PMID 30159123, 2018).